IHH (Indian hedgehog signaling molecule)
Diseases named in the same sentence as IHH in open-access papers (continued):
Sharing a sentence is not in itself a finding about the gene and the disease.
gastric adenocarcinoma (1 paper, 2021). "Also, IHH expression level was associated with histological type, as it was significantly lower in well differentiated gastric adenocarcinomas in comparison with moderately or poorly differentiated adenocarcinoma (P < 0.01)." (PMID 33811245, 2021).
hearing loss (1 paper, 2017). "In a clinical sense, recognizing those IHH genes and associated phenotypes may improve our diagnostic capabilities by enabling us to prioritize the screening of particular gene(s) such as synkinesia (ANOS1), dental agenesis (FGF8/FGFR1) and hearing loss (CHD7)." (PMID 29280744, 2017).
hypogonadism (1 paper, 2019). A disorder characterized by decreased function of the gonads. "An interfering role of BMI is also unlikely as the disrupting variants in IHH genes here considered should not represent a cause of obesity independent of hypogonadism." (PMID 30669598, 2019).
ischemia (1 paper, 2023). A hypoperfusion of the BLOOD through an organ or tissue caused by a PATHOLOGIC CONSTRICTION or obstruction of its BLOOD VESSELS, or an absence of BLOOD CIRCULATION. "IHH is involved in the Hedgehog (HH) pathway, whose functions include maintenance of the endothelial compartment and orchestrating revascularization upon vessel occlusion-induced ischemia." (PMID 37098010, 2023).
leukemia (1 paper, 2017). A malignant (clonal) hematologic disorder, involving hematopoietic stem cells and characterized by the presence of primitive or atypical myeloid or lymphoid cells in the bone marrow and the blood. "Joint expression of SPI1 and IHH results in the appearance of self-renewing leukemic cancer stem cells erythroid progenitors are infected with viruses with subsequent occurrence of leukemia." (PMID 28031533, 2017).
liver fibrosis (1 paper, 2021). "Administration of miR-223 inhibited liver fibrosis by inhibiting the transcriptional coactivator with PDZ-binding motif (TAZ)-Indian hedgehog (IHH)-GLI Family Zinc Finger 2 (GLI2) pathway via the crosstalk between hepatocytes and HSCs." (PMID 33867837, 2021). "In the current study, we demonstrated that overexpression of miR-223 in hepatocytes can also ameliorate CCl4-induced liver fibrosis by secreting TAZ-targeting IHH and by releasing miR-223-enriched EVs." (PMID 33867837, 2021). "Of note, overexpression of miR-223 in hepatocytes ameliorates CCl4-induced liver fibrosis along with the hepatic downregulation of TAZ and IHH." (PMID 33867837, 2021).
lung carcinoma (1 paper, 2020). "Further studies are needed to test if IHH has a role in the homeostasis of the adult lung epithelia or if it is unique to lung cancers." (PMID 32108165, 2020).
meningioma (1 paper, 2023). A generally slow growing tumor attached to the dura mater. "We further characterized the meningiomas that acquired a tandem duplication involving IHH using H3K27ac ChIP-seq and HiChIP, discovering that the tandem duplication is associated with super-enhancer hijacking by IHH." (PMID 37805627, 2023). "The distinct genomic profiles of IHH-activating meningiomas in these locations suggest the existence of epigenetically unique cell populations, whereby differences in chromatin state confer variable sensitivities to specific genomic events." (PMID 37805627, 2023). "Using RNA-Seq, we demonstrated that meningiomas acquiring SVs on 2q35 and 7q36.3 led to ectopic expression of the Hh ligands, IHH and SHH, respectively, and Hh pathway activation." (PMID 37805627, 2023). "The complex rearrangements found in IHH-activating meningiomas result in marked chromosomal disruption and resulting changes in epigenetic regulation may induce Hh pathway sensitivity in an otherwise resistant cell population." (PMID 37805627, 2023). "As in those disorders, the meningioma-specific events we have discovered exhibit remarkably similar boundaries, suggesting that precise breakpoints are necessary to enable de novo super-enhancer interactions with IHH (as has been suggested in other forms of cancer)." (PMID 37805627, 2023).
Noonan syndrome (1 paper, 2020). Noonan Syndrome (NS) is characterized by short stature, typical facial dysmorphism and congenital heart defects. "Normal SHP2/PTPN11 function seems to act as IHH suppressor, and experiments in mice have documented decreased IHH levels in Noonan syndrome caused by germline activating mutations in PTPN11." (PMID 32404184, 2020).
oral cancer (1 paper, 2025). "The PRKD1 E710D hotspot mutation and protein expression of PRKD1 and HH components (SHH, IHH, SMO, and GLI‐1) were detected in PAC regardless of tissue invasion, although HH proteins contributed to the morphogenesis of this rare oral cancer." (PMID 40930949, 2025).
ovarian carcinoma (1 paper, 2016). A malignant neoplasm originating from the surface ovarian epithelium. "In the COV318 ovarian cancer cell line, BMP4 treatment induced IHH rather than SHH." (PMID 26755648, 2016).
ovarian tumors (1 paper, 2016). "Consistent with previous results, GLI1 and GLI3 (HH pathway transcriptional effectors), PTCH1 (HH signaling repressor and target gene), SMO (HH signaling activator), IHH and SHH (HH pathway ligands) were expressed in ovarian tumors, albeit at variable levels." (PMID 26755648, 2016).
pancreatic ductal adenocarcinoma (1 paper, 2021). An infiltrating adenocarcinoma that arises from the epithelial cells of the pancreas. "Also, immunohistochemical study indicated that IHH expression was increased in pancreatic ductal adenocarcinoma in comparison with paracancer tissue and benign lesions, and this expression was associated with tumor grade, lymph node metastasis, tumor invasion, and poor overall survival." (PMID 33811245, 2021).
polycystic ovary syndrome (1 paper, 2023). A disorder that manifests as multiple cysts on the ovaries. "In fact, in a previous study on women with polycystic ovary syndrome (PCOS), one of the most common endocrine disorders in women, IHH was abnormally highly expressed in the PCOS tissue." (PMID 36829526, 2023).
puberty (1 paper, 2023). The process of sexual maturation mediated by the neuroendocrine system in mammals. "It has been previously observed that variants in IHH genes can also cause self-limited delayed puberty, even sometimes within the same kindreds, indicating that self-limited delayed puberty shares an underlying pathophysiology with IHH." (PMID 37600690, 2023).
Sepsis (1 paper, 2014). Sepsis is defined as life-threatening organ dysfunction caused by a dysregulated host response to infection. "ROC analysis was then performed on ACVR2A, FOXO1, IHH and STK4 to evaluate the predictive valueof sepsis mortality." (PMID 24303815, 2014). "Dynamic changes in serum ACVR2A, FOXO1, IHH and STK4 levels in patients with sepsis during theirhospitalization in ICUs were evaluated." (PMID 24303815, 2014). "To date, nofunctional studies addressing the role of IHH and STK4 in sepsis have been reported." (PMID 24303815, 2014).
Simpson-Golabi-Behmel syndrome (1 paper, 2024). Simpson-Golabi-Behmel syndrome is a rare X-linked multiple congenital anomalies syndrome, characterized by pre- and postnatal overgrowth, distinctive craniofacial features, variable congenital malformations, organomegaly and an increased tumor risk. "Loss-of-function variants in GPC3 cause the Simpson-Golabi-Behmel syndrome type 1 (SGBS), at least in part, due to increase of IHH signaling." (PMID 38894719, 2024).
thymic atrophy (1 paper, 2024). "Perhaps, infection-associated thymic atrophy leads to downregulation of tRF-25-SP5830MMUK, which upregulates IHH and causes thymocyte loss." (PMID 39582886, 2024).
tumor (30 papers, 2013 to 2025). "Nonetheless, even with our limited sample size, we found that the well-known association between survival and tumor size was further refined when IHH levels were taken into consideration." (PMID 24799831, 2014). "Subgroup analysis by tumor size and IHH expression indicated that the well-known association between survival and tumor size was further refined when IHH levels were taken into consideration." (PMID 24799831, 2014). "Previous literature as well as work by our group has shown that PDAC cells secrete elevated levels of Hh ligands (SHH, IHH), which are thought to confer tumor-promoting stromal features." (PMID 40508010, 2025). "In the context of PDA, HH ligands (primarily sonic hedgehog [SHH] and indian hedgehog [IHH]) are secreted by tumor cells and bind to the canonical receptor patched 1 (PTCH1) on fibroblasts." (PMID 35867772, 2022). "In contrast to the activation of hedgehog in tumor cells, activation of the canonical Hh signaling pathway in stromal cells by IHH was shown to suppress tumor growth and metastases, in part, by limiting ROS activity." (PMID 33968932, 2021). "Loss of IHH, another Hh ligand, by in vivo CRISPR led to more aggressive tumor growth suggesting that IHH, rather than SHH, activates the pathway in stroma to drive its tumor suppressive effects—a novel role for IHH in the lung." (PMID 32108165, 2020). "Early abrogation of the pathway by an anti-SHH/IHH antibody 5E1 led to significantly worse survival with increased tumor and metastatic burden." (PMID 32108165, 2020). "Our studies here highlight the tumor suppressive roles of stromal Hh pathway activation by IHH via limiting hypoxia and ROS activity through angiogenesis and reinforce the anti-oncogenic role of stroma early in the tumorigenic process." (PMID 32108165, 2020). "The data here suggest that IHH is sufficient to suppress tumor initiation and growth and that SHH is dispensable for LAD tumorigenesis." (PMID 32108165, 2020). "In line with our observations, it has been shown that treatment with Vismodegib or IHH knockout mouse models lead to increased tumour occurrence and larger tumours." (PMID 30926792, 2019). "IHH expression is upregulated in the cancer cells from cluster 2 tumours where regulatory chromatin accessibility increases." (PMID 28859074, 2017). "Additional work will be necessary to determine if this relates to currently undefined differences in SHH and IHH signaling or alternate pathways promoting tumor cell IHH secretion." (PMID 26755648, 2016). "Since the Hedgehog pathway controls the proliferation of chondrocytes during bone development, an interaction between IHH and proliferation, which presumably contribute to tumor size, likely exists." (PMID 24799831, 2014). "In the clinic, the administration of an IHH antagonist to cure tumor growth is a common strategy." (PMID 38409269, 2024). "IHH, PTCH1 and GLI1 expression levels were strongly associated with each other and with tumour proliferation in human osteosarcoma cell lines and primary tumour specimens." (PMID 36457847, 2022). "Treatment of an SCLC patient-derived xenograft (PDX) cell line with recombinant rSHH or viral infection with SMO-M2 accelerated cell proliferation in culture, whereas pharmacologic inhibition, genetic knockdown, or depletion of SHH/IHH by a blocking antibody inhibited tumor cell proliferation." (PMID 36010600, 2022). "In addition, stromal activation of Hh signaling pathways by IHH suppresses tumor growth and metastases through angiogenesis and reduction of reactive oxygen species (ROS) activity." (PMID 33811245, 2021).
tumor (continued). "Identification of factors that negatively regulate IHH production in LAD may serve as targets of small molecule or antibody therapeutics to enhance IHH expression and restrain tumor growth and metastases." (PMID 32108165, 2020). "Thus, IHH induces stromal activation of the canonical Hh signaling pathway to suppress tumor growth and metastases, in part, by limiting ROS activity." (PMID 32108165, 2020). "Likewise, SKOV3 and CAOV-3 tumor cells demonstrated significant induction of SHH while COV318 cells demonstrated significant induction of IHH." (PMID 26755648, 2016). "Moreover, in the small tumor subgroup, patients with low IHH expression had better disease-free survival than those with high IHH expression (P value = 0.0163; HR = 3.19; CI: (0.58, 17.44))." (PMID 24799831, 2014). "Importantly we also noted the presence of IHH on our list of differentially expressed transcripts related to tumor grade." (PMID 23785665, 2013). "Therefore—considering their results—it is interesting to note that both ligand-dependent and ligand-independent mechanisms promote the stimulation of the Hh signaling pathway in OS and, unfortunately, that the ligand-dependent one induced by high IHH levels is responsible for tumor growth." (PMID 39457084, 2024). "However, the tumor suppressor or oncogenic role of IHH in cancer is controversial." (PMID 33811245, 2021). "Thus, mRNA expression data from human primary PCa samples indicate that the level of HH signaling (GLI1 expression) correlates with the proportion of stromal cells in a tumor, and IHH is increased more than the other HH ligands in tumors compared with normal prostate." (PMID 27935821, 2017). "Moreover, the high levels of IHh may lead to larger tumor size, a prognostic factor of OS thereby indicating that activation of Hh signaling is required for OS progression." (PMID 25985215, 2015). "The observation that IHH expression is predictive of outcome in combination with tumor size suggests that IHH expression may be used to improve the prognostic value of tumor size and possibly improve the stratification of patients prior to starting chemotherapy." (PMID 24799831, 2014). "Moreover, the high levels of IHH may lead to larger tumor size, a prognostic factor of OS and indicate that activation of Hh signaling is required for OS progression." (PMID 25085524, 2014). "In the multivariate Cox Proportional Hazards model (n = 23), to assess whether tumor size in combination with the expression of IHH correlates with poor survival, borderline significance (P = 0.0970; HR = 6.4; CI: (0.7, 57.9)) was achieved for high IHH expression group." (PMID 24799831, 2014). "It has been previously reported that latent EBV induces DNA hypermethylation, and that EBV-mediated silencing of tumor suppressor genes, such as IHH and TRABD, favors tumor proliferation." (PMID 32841292, 2020). "A surprising result of our studies was the central role of IHH, instead of SHH, to suppress tumor growth." (PMID 32108165, 2020). "In the tumor, the Hh pathway ligands, SHH and IHH, had undetectable expression consistent with ligand-independent Hh pathway activation following PTCH1 inactivation." (PMID 31362756, 2019). "This paracrine mechanism is characterized by binding of tumor-secreted Hh ligands (SHH, Indian Hedgehog (IHH), or Desert Hedgehog (DHH)) to PTCH1 receptors, and elevated levels of GLI1, GLI2, PTCH1, and SMO genes in the tumor-adjacent stroma." (PMID 31658643, 2019). "In untreated PDX tumours, SHH and IHH were transcribed predominantly in the human-derived tumour epithelium, while Gli1, Ptch1 and Smo were transcribed predominantly in the murine stroma." (PMID 29715275, 2018).
tumor (continued). "Further highlighting the complexity of HH signaling, we demonstrate that both tumor derived SHH and IHH form a signaling loop with CA-MSC-derived BMP4." (PMID 26755648, 2016). "This is the first study reporting that the loss of Fgfr3 function leads to the formation of chondroma-like lesions via downregulation of MEK/ERK signaling and upregulation of IHH, suggesting that FGFR3 has a tumor suppressor-like function in chondrogenesis." (PMID 26091072, 2015). "Our in silico analysis predicted that mir-195-5p binding site was located in the 3′ UTR of IHH, and experimental data indicated that mir-195-5p was significantly down-regulated in tumor samples in comparison with their adjacent non-tumoral tissues." (PMID 33811245, 2021). "The conflicting observations around IHH signalling in normal colon and CRC might arise from the various models used in the studies, such as normal small intestine or colon, different tumour stages, and cancer cell line models." (PMID 30926792, 2019). "Importantly, knockdown of IHH also reduces the efficacy of UNC1999 in vivo, limiting the decrease in tumour growth by 50%." (PMID 30926792, 2019). "The anti-tumor response to the combination of curcumin and OPCs in mice xenograft tumors and organoids derived from primary human CRC tumors correlated with the altered gene expressions of HSPA5, IHH, PDE3B, cyclin D1 and SEC61B." (PMID 30218018, 2018). "The presence of one or more Hedgehog ligand implies that there is selective pressure on tumor cells to express Hedgehog, but that the exact protein expressed is not critical and that either IHH, SHH, or both will suffice." (PMID 25884700, 2015). "IHH, rather than SHH, was demonstrated to be the critical tumor-suppressive Hh ligand through in vivo CRISPR deletion of IHH that recapitulated the phenotype of 5E1 treatment." (PMID 36010600, 2022). "Likewise, loss of IHH, another SHH ligand, by in vivo CRISPR led to more aggressive tumour growth suggesting that IHH, rather than SHH, activates the pathway in stroma to drive its tumour-suppressive effects—a novel role for IHH in the lung." (PMID 36701089, 2023).